GLUD1 (glutamate dehydrogenase 1)
Diseases named in the same sentence as GLUD1 in open-access papers (continued):
Sharing a sentence is not in itself a finding about the gene and the disease.
mental disorder (3 papers, 2012 to 2025). A disease that has its basis in the disruption of mental process. "Additionally, we discuss its emerging clinical significance, with GRID1 mutations associated with neurodevelopmental and psychiatric disorders, and recent findings implicating GluD1 dysfunction in chronic pain." (PMID 41345253, 2025). "Understanding the relationship of behavioral deficits in GluD1 knockout to these mental disorders may reveal novel molecular mechanisms underlying the behavioral abnormalities in these disorders." (PMID 23560106, 2013). "This points to the possibility that dysregulation of GluD1 may be a predisposing factor for a specific domain of mental disorders." (PMID 23560106, 2013). "Further studies are required to fully understand a potential relationship between GluD1 and mental disorders and evaluate details of the GluD1-mediated mechanisms in the regulation of synapses and circuits." (PMID 23560106, 2013). "Together our behavioral and molecular analysis of GluD1 knockout mice strongly implicate that GluD1 dysregulation may lead to behavioral and cognitive deficits observed in mental disorders." (PMID 23560106, 2013). "It is also possible that the behavior exhibited by GluD1 knockout may relate more closely to other mental disorders specifically ASDs and further detailed studies will be required to test this hypothesis." (PMID 22412961, 2012). "Thus, abnormalities in hippocampal function and changes in AMPA/kainate expression in the hippocampus may be involved in the pathophysiology of certain types of mental disorders and behavioral abnormalities similar to those observed in GluD1 knockout." (PMID 22412961, 2012).
cervical cancer (2 papers, 2022 to 2025). A primary or metastatic malignant neoplasm involving the cervix. "Thus, we demonstrated an oncogenic role of circTICRR in cervical cancer and the underlying mechanism by which circTICRR inhibited autophagy, through the binding to HuR protein and stabilizing GLUD1 mRNA." (PMID 35595754, 2022). "For instance, circ‐cTICRR binds with HuR protein, which stabilizes GLUD1 mRNA and increases the level of GLUD1 protein, indicating its oncogenic role in cervical cancer." (PMID 40567251, 2025). "To ascertain the signaling pathway by which circTICRR inhibits autophagy, we performed a RNA-seq and found significantly down-regulated expression of GLUD1 mRNA in the cervical cancer cells with circTICRR knockdown." (PMID 35595754, 2022). "Together, our results suggest that the interaction between circTICRR and HuR, via F287/F289 in RRM3 domain of HuR, stabilizes GLUD1 mRNA and elevates the level of GLUD1 protein, leading to inhibition of autophagy in cervical cancer cells." (PMID 35595754, 2022). "We further investigated the effect of GLUD1 on the viability and autophagy of cervical cancer cells." (PMID 35595754, 2022). "Together, our results suggest that circTICRR interacts with the HuR protein, subsequently enhancing the stability of GLUD1 mRNA in cervical cancer cells." (PMID 35595754, 2022). "In this study, we found that circTICRR promoted cervical cancer cells proliferation and inhibited apoptosis in vitro and in vivo through restraining autophagy, and that circTICRR functioned via directly interacting with HuR protein to stabilize GLUD1 mRNA." (PMID 35595754, 2022). "In this study, we observed that GLUD1 knockdown promoted autophagy, induced apoptosis, and inhibited cell proliferation, while overexpression of GLUD1 reversed autophagy activated by circTICRR knockdown, suggesting that GLUD1 is involved in circTICRR regulating autophagy in cervical cancer cells." (PMID 35595754, 2022).
cognition disorders (2 papers, 2013 to 2025). "Glutamate delta 1 receptor (GluD1) has various functional roles in the brain, such as high-frequency hearing, synapse formation and maintenance, and regulation of cognition disorders and neurodevelopmental disease." (PMID 41515947, 2025). "Moreover, substantial evidence links GluD1 to high-frequency hearing, several neuronal diseases, as well as cognition disorders." (PMID 41515947, 2025).
diabetes (2 papers, 2024 to 2026). "We observed increased Glud1 expression in one Müller cell cluster in diabetes." (PMID 41266111, 2026).
gastric cancer (2 papers, 2022 to 2026). A primary or metastatic malignant neoplasm involving the stomach. "GLUD1 enhanced gastric cancer cell proliferation, migration and invasion by activating the Notch signaling pathway." (PMID 36203437, 2022). "Clinical analysis reveals that elevated GLUD1, PRMT7, and meGLUD1(R76) levels correlate with tumor progression in gastric cancer." (PMID 41876450, 2026).
ovarian carcinoma (2 papers, 2023 to 2026). A malignant neoplasm originating from the surface ovarian epithelium. "Loss of GLUD1 impaired anoikis resistance and reduced metastatic capacity of ovarian cancer cells in vitro, while markedly suppressing peritoneal dissemination and prolonging survival in vivo." (PMID 41786885, 2026). "• Sevoflurane upregulated but propofol downregulated the GLUT1, MPC1, and GLUD1 expressions of ovarian cancer cells." (PMID 36207479, 2023). "The current study demonstrated that sevoflurane upregulated GLUT1, MPC1, and GLUD1 expressions of ovarian cancer cells, while propofol downregulated the expressions of these molecules." (PMID 36207479, 2023).
pancreatic ductal adenocarcinoma (2 papers, 2016 to 2020). An infiltrating adenocarcinoma that arises from the epithelial cells of the pancreas. "A study demonstrated that one of the mechanisms of KRAS in inducing pancreatic ductal adenocarcinoma is by up-regulating GOT1 and inhibiting glutamate dehydrogenase 1 (GLUD1), thus reprogramming glutamine metabolism." (PMID 32266153, 2020).
renal carcinoma (2 papers, 2022 to 2023). A carcinoma arising from the epithelium of the renal parenchyma or the renal pelvis. "Previous work revealed that high expression of glutamate dehydrogenase 1 (GLUD1) is detrimental to the survival of renal cancer cells in unfavorable nutritional environments (such as amino acid deficiency) and is significantly associated with good prognosis in KIRC patients." (PMID 37627013, 2023). "Therefore, utilizing drugs targeting GLUD1 metabolism may synergistically enhance renal cancer immunotherapy through metabolic reprogramming of the TME." (PMID 36203437, 2022).
Acidosis (1 paper, 2018). Abnormal acid accumulation or depletion of base. "Metabolic acidosis results in the upregulation of enzymes which direct the metabolism of glutamine towards ammoniagensis (GLS and glutamate dehydrogenase 1) and gluconeogenesis (PEPCK)." (PMID 29618784, 2018).
Beckwith-Wiedemann syndrome (1 paper, 2024). Beckwith-Wiedemann syndrome (BWS) is a genetic disorder characterized by overgrowth, tumor predisposition and congenital malformations. "Genetic studies were negative for mutations in ABCC8, KCNJ11, GCK, or GLUD1 genes, multiple endocrine neoplasia (MEN) type 1, and Beckwith-Wiedemann syndrome." (PMID 39170749, 2024).
Cerebral ischemia (1 paper, 2016). Restriction of arterial blood supply to the brain associated with insufficient oxygenation to support the metabolic requirements of the tissue. "With the docking design to galangin, the six proteins (GLUD1, GLUL, GLS, CTH, GOT2 and HP) with high affinity might become its targets for cerebral ischemia." (PMID 27058522, 2016).
citrullinemia (1 paper, 2021). Citrullinemia is an autosomal recessively inherited disorder of urea cycle metabolism and ammonia detoxification characterized by elevated concentrations of serum citrulline and ammonia. "Metabolic diseases were observed in nine (6.2%) patients: three with citrullinemia, two with Leigh disease, one with ornithine transcarbamylase deficiency, one with pyridoxine dependent epilepsy, one with fumarase deficiency, and one with glutamate dehydrogenase 1 deficiency." (PMID 33499362, 2021).
colorectal tumor (1 paper, 2024). "Proteins that regulate glycolysis (PGK1, PGAM1, ENO1, PKM, TKT), ammonia detoxification (GLUD1), and other metabolic pathways (LDHA, GAPDH, MDH2) were reported to be differentially expressed in mouse xenograft colorectal tumor models with different radio- responsiveness." (PMID 38410100, 2024).
congenital hyperinsulinism (1 paper, 2018). "GDH-HI (hyperinsulinism hyperammonemia syndrome; HI/HA syndrome) caused by GLUD1-activating mutations is the second most common cause of congenital hyperinsulinism (CHI MIM256450), which is a genetic and phenotypic heterogeneous group of disorders associated with dysregulated insulin secretion." (PMID 30306091, 2018).
COVID-19 (1 paper, 2023). A disease caused by infection with severe acute respiratory syndrome coronavirus 2. "Likewise, glutaminolysis was used as an alternative pathway, evidenced by upregulation of glutamate oxidation-regulating genes (GLUD1, DGLUCY) in COVID-19(+) CD8+TM." (PMID 37029220, 2023).
dementia (1 paper, 2018). Loss of intellectual abilities interfering with an individual's social and occupational functions. "Within TCX, expression of GLUD1 (t = −2.255, padj = 0.036) and NDRG2 (t = −2.120, padj = 0.048) were significantly lower in subjects with dementia versus dementia-free subjects." (PMID 30120299, 2018).
developmental arrest (1 paper, 2014). "It seems as if the expression of CPS1, OTC, ASL, NAGS and GLUD1 in dogs with CPSS has come to a developmental arrest which prevented them to normalize after closure of the shunt." (PMID 24945279, 2014).
developmental delay (1 paper, 2024). "The GluD1 M4 domain also appears intolerant to variation using the 3D MTR method, and one variant (GluD1-A817T) from a patient with developmental delay and other neurological features was identified in this region and was absent from the gnomAD database." (PMID 37944084, 2024).
hyperuricemia (1 paper, 2018). An abnormally high level of uric acid. "More studies are needed in the future to 1) confirm the biological function of FAM35A and 2) investigate the potential association between GLUD1 and hyperuricemia (and its related traits)." (PMID 29942023, 2018).
liver diseases (1 paper, 2020). "Moreover, expression of a number genes—potential therapeutic targets in liver diseases—including EGFR, GLUD1, GNL3, and RGS5, has been shown to be modified by dietary fats and should be further investigated in this regard." (PMID 32961898, 2020).
lung adenocarcinoma (1 paper, 2025). A carcinoma that arises from the lung and is characterized by the presence of malignant glandular epithelial cells. "Research has demonstrated that glutamate dehydrogenase (GLUD1) is expressed at a high level in lung adenocarcinoma cells, and lysine 503 (K503) has been identified as the primary ubiquitination site of GLUD1." (PMID 40598593, 2025).
lupus (1 paper, 2025). "Activated cTfh cells showed increased SLC1A5 and GLS expression (but not GLUD1) (orange group), indicating active glutamine metabolism, known to be critical for Th17 cells and disease severity in lupus mice." (PMID 40693461, 2025).
macrosomia (1 paper, 2024). "Patients with KATP variants tended to be macrosomia at birth, had earlier onset time, exhibited a lower response rate to non-surgical interventions, while displayed a higher level of serum C-peptide than those with GLUD1 variants." (PMID 40302972, 2024).
methylmalonic acidemia (1 paper, 2025). A genetically heterogenous inherited disorder characterized by abnormalities in the metabolism of lipids and proteins. "The remaining IMDs included two cases (11.2%) of glutamate dehydrogenase deficiency (GLUD-1), one case (5.5%) of methylmalonic acidemia (MMA), and one case (5.5%) of HFI." (PMID 39861352, 2025).
Pain (1 paper, 2021). An unpleasant sensory and emotional experience associated with actual or potential tissue damage, or described in terms of such damage. "In inflammatory and neuropathic pain models, GluD1 and its partner cerebellin 1 (Cbln1) are downregulated while AMPA receptor is upregulated." (PMID 34685624, 2021).
pulmonary arterial hypertension (1 paper, 2021). Pulmonary arterial hypertension (PAH) is a group of diseases characterized by mean pulmonary artery pressure >20 mmHg and elevated pulmonary arterial resistance leading to right heart failure. "In the rat model of pulmonary arterial hypertension (PAH), MSC-EVs upregulated both PDH and Glutamate Dehydrogenase 1 (GLUD1) gene expression in an hypoxic environment and increased glucose oxidation by TCA cycle." (PMID 33796099, 2021).
Rett syndrome (1 paper, 2022). A severe neurodevelopmental disorder affecting the central nervous system.
cancer (72 papers, 2015 to 2025). A tumor composed of atypical neoplastic, often pleomorphic cells that invade other tissues. "Several studies have demonstrated that cancer progression is associated with multiple classical pathways, in our study, protein expression of GLUD1 was associated with alterations in those pathways compared to normal tissues." (PMID 38245763, 2024). "GLUD1 is integral to glutamine metabolism, a process critical for cancer cell survival and immune cell function." (PMID 40861812, 2025). "Epigallocatechin gallate (EGCG), an inhibitor of GLUD1 and GLUD2, has been shown to suppress the proliferation of IDH1-mutated cancer cell lines in vitro." (PMID 40710547, 2025). "GLUD1, known for its role in catalyzing the reversible deamination of glutamate to produce α-KG, plays a pivotal role in α-KG synthesis in cancer cells." (PMID 38773972, 2024). "PLAG1 also drives cancer metastasis via its transcriptional regulation of isocitrate dehydrogenase (NADP)-specific glutamate dehydrogenase 1 (Gdh1), mediating anti-anoikis and pro-metastatic signalling within cancer cells." (PMID 38240991, 2024). "GLUD1 can regulate redox homeostasis in cancer cells by metabolic reprogramming in terms of enhancing aerobic glycolysis and protein translation, which are vital for tumor proliferation." (PMID 39266576, 2024). "In the previous study, we carried out quantitative proteomic detection of cancer and normal liver tissues of clinical HCC patients, and found that the protein expression level of GLUD1 in cancer tissues was significantly decreased." (PMID 38216781, 2024). "In cancer cells, conversion of Glut into α-ketoglutarate (α-KG) relies on glutamate dehydrogenase (GLUD1), glutamic-pyruvic transaminase 2 (GPT2) or glutamic-oxaloacetic transaminase 2 (GOT2)." (PMID 38424041, 2024). "The results of GLUD1 expression with multiple cancer-related pathways and the enrichment analysis of its related genes initially revealed the possible pathways of GLUD1 regulation in ccRCC." (PMID 38245763, 2024). "The relationship between SIRT5 and GLUD1 in cancer metabolism, particularly in CRC, is of significant interest." (PMID 38773972, 2024). "Although upregulation of FASN, GLUD1, and G6PD in the high-risk group barely missed statistical significance, these enzymes deserve attention given their biological significance in cancer and metabolism." (PMID 37760474, 2023). "Glutamine can be transformed into glutamate and further converted to α-ketoglutarate under the catalyzation of GLUD1 for use in the TCA cycle generating crucial intermediates for cancer growth and survival." (PMID 36207479, 2023). "GLUD1 is not only required for cancer cells to maintain the TCA cycle in order to accomplish rapid proliferation and development, but it can also activate mTORC1." (PMID 37048450, 2023). "This pilot study on a small coumarin compound, decursinol angelate, showed inhibition against glutamate dehydrogenase 1, which regulates the glutaminolysis involved in fueling cancer cells." (PMID 37509203, 2023). "In human cancer cells, GLUD1 expression is generally elevated to ensure that the cells produce energy for rapid growth." (PMID 35847357, 2022). "GLUD1 activation can also support cancer cell growth through NH+4 fixation, as increased concentrations of NH4+ can support proliferation, migration, and survival of metastatic cancer cells." (PMID 35048115, 2022). "In this study, we described GLUD1 as a novel tumor suppressor in ccRCC, which was different from tumor-promoting role in other cancers." (PMID 36203437, 2022). "Most cancer cells use glutamate dehydrogenase 1 (GLUD1) to convert glutamine-derived glutamate into α-KG in the mitochondria to supply the Krebs cycle." (PMID 35178152, 2022). "Several reports from other cancers showed that patients with high GLUD1, ANXA4, and PLXDC1 expression have low overall survival, but our findings in CCA are contrasting." (PMID 33193605, 2020).